IL10 (interleukin 10)
Diseases named in the same sentence as IL10 in open-access papers (continued):
Sharing a sentence is not in itself a finding about the gene and the disease.
colitis (continued). "The anti-inflammatory effect of fenofibrate by delaying colitis onset and progression in Il10−/− mice indicates that IL10 is not required in PPARα signaling." (PMID 20671959, 2010). "IL-10 knock-out mice develop colitis if they are not kept in germ-free environment, and the administration of IL-10 ameliorates the inflammation in animal and in vitro models." (PMID 20509889, 2010). "Elevated levels of IL-4 were also seen in sash mice singly deficient in mast cells and in TNF-deficient mice that do not develop colitis under these conditions, compared with Il10−/− mice that develop severe colitis." (PMID 20808919, 2010). "Infected Il10−/− and DKO mice both demonstrated severe colitis that was slightly increased in the absence of mast cells (mean histologic score = 43±1 in Il10−/− mice vs. 48±2 in DKO mice; p = 0.03)." (PMID 20808919, 2010). "Although this bacterium has been shown to induce colitis in certain strains of mice, one study reported that germ-free IL-10−/− mice monoassociated with H. hepaticus (the same strain as the one used here) did not develop colitis." (PMID 19401779, 2009). "A recent report has shown that the ratio between IL-10 and IL-12 production after treatment of human peripheral blood mononuclear cells with probiotics, was predictive of in vivo probiotic activity in the TNBS colitis mouse model." (PMID 19756155, 2009). "A recent study has demonstrated that lacking IL-10-producing Treg is inductive to skin and colon inflammation." (PMID 19272184, 2009). "None of the 19 uninfected C57BL/6 IL-10-/- mice with spontaneous colitis that we have observed in either our breeding colony or in experiments have exhibited bloody contents in the gut lumen." (PMID 19296832, 2009). "While the cellular mechanism(s) and response(s) mediating Mycobacteria-enhanced IBD have not been entirely demonstrated, recently we showed that colitis in IL-10-/- mice was driven in part by 85B Ag-specific CD4+ T cell responses." (PMID 18533024, 2008). "To address the leukocyte subsets responsible for colitis progression, we assessed the ex vivo expression of chemokines and cytokines by MLN-, PP-, and LP-derived cell subsets in IL-10-/- mice challenged with live or heat-killed M. avium paratuberculosis bacilli." (PMID 18533024, 2008). "Taken together, these studies demonstrate that short-term treatment with a transcriptional inhibitor of TNF production does not decrease the severity of acute and chronic DSS colitis or piroxicam-accelerated colitis in IL-10-/- mice." (PMID 18331642, 2008). "Indeed, it is already demonstrated that TLR9 can trigger anti-inflammatory functions in experimental colitis, and it has been shown that upon TLR-signaling the levels of the anti-inflammatory cytokine IL-10 can be enhanced within dendritic cells." (PMID 18974879, 2008). "Colonic levels of TNF were elevated in untreated IL-10-/- mice with colitis compared with wild type mice without colitis." (PMID 18331642, 2008). "B. vulgatus mpk mono-colonized mice only showed expression of IL-6 mRNA, whereas E. coli mpk mono-colonized mice, prone to develop colitis and SPF IL-2−/−-mice already suffering from colitis, revealed high levels of IL-1α, IL-1β, TNF-α, IFN-γ, IL-10 and IL-6 mRNA in the intestine." (PMID 18545662, 2008). "Unlike, in B. vulgatus mpk mono-colonized mice which do not develop colitis we observed neither IFN-γ or IL-17 nor IL-10 or IL-4 expression indicating that semi-mature LP DC did not lead to T-cell polarization." (PMID 18545662, 2008). "The colitis, developed after TNBS administration, largely enhanced the expression of TNF-α, IL-6, IL-1β, IL-12, IL-23, IL-17, Cox-2, IL-10, and IFNβ genes, with a fold increase in mRNA levels of 28.7, 89.26, 303.9, 36.03, 9.14, 329.00, 32.07, 10.89, and 24.16, respectively compared to healthy mice." (PMID 17375199, 2007).
colitis (continued). "For example, Clostridium butyricum and Bacteroides fragilis-derived polysaccharide A (PSA) have been shown to enhance IL-10 production in macrophages and Treg cells, respectively, through Toll-like receptor 2 (TLR2)-dependent signaling, ultimately contributing to the amelioration of colitis." (PMID 41511071, 2026). "In 12 patients in remission, 15 with mild‐moderately active disease and 6 with severe colitis, concentrations of interleukin‐17, IL10, interferon‐γ, interleukin‐8 and interleukin‐6, but not tumor necrosis factor‐α or interleukin‐12p70, significantly reflected disease activity." (PMID 40584280, 2025). "Furthermore, L. paracasei mitigated colitis through MIP-2 suppression and IL-10 upregulation." (PMID 41301527, 2025). "We decided to use the DSS colitis model to avoid confounding effects of immunodeficiency on beta‐amyloid pathology (SCID/RAG2‐/‐) and because IL‐10 crossed with beta‐amyloid overexpressing mice have reduced deposition, showing that IL‐10 plays a role in beta‐amyloid pathology." (PMID 40457749, 2025). "Animal models highlight the importance of the microbiota: genetically engineered mice lacking interleukin-2 (IL-2), interleukin-10 (IL-10), or human leucocyte antigen-B27 (HLA-B27) do not develop colitis under sterile conditions, but do so when colonised with a gut microbiota." (PMID 41356879, 2025). "Empirical evidence has demonstrated that the Src inhibitor dasatinib exacerbates colitis by elevating TNF‐α levels, which occurs through the suppression of IL‐10, possibly involving the activation of the Src‐Akt signaling pathway to facilitate IL‐10 production." (PMID 40895135, 2025). "IL-10-/- mice did not develop colitis symptoms during the experiment." (PMID 39843997, 2025). "This suggests that floxing itself may have altered Pak1, which conferred protection from colitis and tumorigenesis upon AOM/DSS, but not from colitis upon total loss of IL10." (PMID 40783411, 2025). "Furthermore, we also demonstrated that targeted delivery of IL-10 by AT-MSC reduces colitis without forming intestinal polyps or inducing colon cancer." (PMID 39990215, 2025). "Many studies have shown that CB or AKK can play a protective role in mouse colitis by regulating some key components related to the inflammatory response, such as pro-inflammatory cytokines (IL-1β, IL-6, and TNF-α) and anti-inflammatory cytokines (IL-4 and IL-10)." (PMID 39840995, 2025). "Additionally, the bacteriocin it secretes (e.g., lactocin Johnsonii) can activate naive macrophages to differentiate into CD206+ macrophages and induce the release of IL-10 via the TLR1/2-STAT3 pathway, alleviating experimental colitis and further enhancing anti-inflammatory and probiotic effects." (PMID 41463870, 2025). "In the model, IL-10-/- mice treated with nanoparticles surprisingly did not develop colitis." (PMID 40149930, 2025). "Moreover, adoptive transfer of Prdm1-deficient Treg cells into Rag2−/− mice failed to suppress the T cell–induced colitis, likely due to their defective IL-10 production." (PMID 40680114, 2025). "Indeed, SvEv129 IL-10–/– pups can be protected from developing colitis by cross-fostering with dams without MMTV infection." (PMID 39817448, 2025). "Moreover, deletion of GC-C and Il-10 resulted in early-onset and more severe colitis than in mice without Il-10 alone." (PMID 40801095, 2025). "Also, intestinal lamina propria macrophages lacking the expression of Il10 showed increased mTORC1 activity, mitochondrial reactive oxygen species (ROS) production, and inflammasome activation, and this might have contributed to the development of colitis in Il10-deficient mice." (PMID 38542140, 2024). "Previously, SEA has been shown to significantly reduce the severity of 2,4,6-trinitrobenzene sulfonic acid (TNBS)-induced colitis and dextran sulfate sodium (DSS)-induced colitis in a mouse model by increasing the number of FoxP3+ Treg cells and secretion of Th2 cytokines, including IL-10." (PMID 39481080, 2024).
colitis (continued). "To gain a deeper understanding of the mechanism by which TP2 alleviates colitis, we utilized ELISA technology to assess typical pro-inflammatory and anti-inflammatory cytokines in rats’ colonic tissues, including TNF-α, IFN-γ, IL-1β, IL-6, IL-10, IL-17A, IL-22, and IL-23." (PMID 39776580, 2024). "Akk supplementation can restore Tregs and IL-10 levels but may not impact IL-17 levels in colitis mice, highlighting the intricate nature of the inflammatory environment." (PMID 39734222, 2024). "IL-10 signalling in macrophages but not T-cells has also been reported to induce regulatory phenotypes that are required for the therapeutic response to anti-TNF treatment in murine colitis." (PMID 38903247, 2024). "Moreover, cutaneous application of capsaicinincreased colonic IL-17 and IL-10 levels regardless of colitis induction.No other effect of capsaicin was evidenced in the other cytokines." (PMID 39022369, 2024). "Similarly, neonatal maternal separation stress also exacerbates colonic permeability and colitis in naturally occurring IBD in IL-10 KO mice, but this psychological stress alone did not induce colitis in naïve mice." (PMID 38491103, 2024). "Furthermore, mice lacking both IL-10 signaling and VLC ceramide synthesis showed reduced immune cell infiltration into the colon compared with Il10-KO mice, highlighting the proinflammatory effects of VLC ceramide accumulation in the context of impaired IL-10 signaling in colitis." (PMID 39132450, 2024). "Interestingly, germ-free IL-10 knockout mice do not develop spontaneous colitis, suggesting a crucial role of external pathogens in the onset of colitis." (PMID 39249550, 2024). "IL-19 is an activator of IL-10 transcription, and therefore, there is a hypothesis that might ameliorate active colitis; however, there is no sufficient data to support this." (PMID 39007024, 2024). "This study found that compared with colitis models induced by DSS, expression levels of NO, TNF-α, IL-1β, and IL-6 were remarkably reduced in the peripheral blood and colon tissues of colitis mice pre-treated by B. tequilensis YB-2, while expression levels of IL-10 and IL-4 significantly increased." (PMID 38998101, 2024). "The oral intervention of L. paracasei BNCC345679 may potentially help restore Akkermansia and Lactobacillus population, which may drive an increase in IL-10 levels, positively affect the cohesion of the mucus layer, and maintain gut homeostasis, which may relieve DSS-induced colitis." (PMID 38601942, 2024). "Animal experiments using a DSS-induced colitis-mouse model revealed that oral administration of Trp, abundantly contained in ED, attenuated inflammation, and its effective mechanism may involve a decrease in TNF-α and an increase in IL-10." (PMID 38542428, 2024). "DSS-induced colitis did not significantly alter IL-10 levels compared to the healthy control." (PMID 39682761, 2024). "SNS significantly reduced colonic inflammation, similar to the effects of vagus nerve stimulation (VNS), by modulating autonomic function and cytokine production (decreased TNF-α, IL-6, and IL-17A, increased IL-10), indicating potential therapeutic utility for IBD treatment." (PMID 39605787, 2024). "Likewise, HY2782 showed effective IL-10+ and RORγt+ Helios− Treg induction in the siLP and cLP during healthy conditions but failed to protect mice against AD and colitis effectively." (PMID 38542701, 2024). "The central hypothesis this study sought to test was whether sex plays a role in the phenotype of colitis developed in a murine model of IBDs, since proper documentation characterizing the sex-based differences in IL-10−/− mice is lacking." (PMID 37373511, 2023). "Abnormal immune responses in the gut are a feature of colitis, which is characterized by the increase of inflammatory cytokines (TNF-α, IL-1β, IL-6, etc) and decrease of anti-inflammatory cytokines, such as IL-10, and these changes are observed in patients with IBD and DSS-induced colitis mice." (PMID 37297494, 2023).
colitis (continued). "In parallel, a significant increase of the immunosuppressive cytokine interleukin (IL)‐10 and a trend towards reduced tumour necrosis factor (TNF) expression was noticed in SHP‐deficient mice at the peak of DSS colitis at day 7, while LRH‐1 expression was not different." (PMID 36861295, 2023). "In colitis mouse models, bile acids can effectively limit M1 macrophages to secret proinflammatory cytokines such as TNF-α, IFN-γ, IL-6, and IL-12, and increase the binding of macrophages to IL-10 gene promoter and differentiation into IL-10 secreting M2 macrophages." (PMID 38169949, 2023). "The results showed that colitis was dramatically ameliorated in the XJS-treated rats as evidenced by relief of clinical symptoms and histopathological damages, downregulation of pro-inflammatory cytokines IL-6, IL-17 and TNF-α, and upregulation of anti-inflammatory cytokine IL-10." (PMID 37153794, 2023). "Additionally, TNBS-induced colitis was not prevented in IL-10−/− mice, indicating that IL-10 is required for LcrV-mediated protection against IBD." (PMID 37049407, 2023). "Similar to our findings, the serum level of IL-10 increased, and the plasma level of TNF-α was reduced after 14 days of TAX-treatment in a model of dextran sulfate sodium-induced colitis in mice (when compared to mice with colitis induced by dextran sulfate sodium)." (PMID 37628795, 2023). "GH also dampened the pro-inflammatory cytokine profile and upregulated IL-10 production, in agreement with the improved remission of inflammation and mucosal repair during recovery in the acute dextran sodium sulfate (DSS)-induced colitis model in bovine GH-overexpressing mice." (PMID 37475858, 2023). "Rather, it was shown that IL-10 secreted by host non-T cells is responsible for preventing colitis." (PMID 37197653, 2023). "Surprisingly, IL-10−/− mice treated with PELNs-H failed to develop acute colitis." (PMID 37653406, 2023). "Convincing data have demonstrated that IL-10-producing B cells, termed regulatory B cells (Bregs) in 2002 by Bhan and collaborators, can suppress inflammatory responses in experimental autoimmune encephalomyelitis (EAE), collagen-induced arthritis (CIA) and colitis." (PMID 35725835, 2023). "Conditional knock-out of IL-10 in Tregs does not result in systemic autoimmunity but leads to inflammation specifically in the lungs and colon, whereby the unchecked immune response in the colon manifests as spontaneous colitis." (PMID 38107848, 2023). "Nevertheless, no IL-10 activation was observed, which functions as an anti-inflammatory mediator to downregulate the expression of Th1-derived cytokines, and promote IL-4, classified as Th2-derived cytokines to reduce colitis." (PMID 37509556, 2023). "ES from the human hookworm Ancylostoma caninum, given to mice daily i.p. during chemically induced colitis, has been shown to exert a modest reduction in pathological scores as well as the inflammatory cytokines, IFN-γ, and IL-17, and also to raise IL-4 and IL-10 responses." (PMID 36855464, 2023). "Oral administration of OA in a mice model of colitis significantly inhibited colon shortening and myeloperoxidase activity, displayed potent anti-inflammatory properties by reducing the activation of TNF-α, IL-1β, IL-17, NF-κB, and MAPK, and increasing the expression of IL-10." (PMID 36829984, 2023). "Some possible explanations might be due to the endogenous production of opioids by T cells in IL10-decificent mice and the lack of colitis in young IL-10 KO mice." (PMID 37049400, 2023). "Colitis did not occur in IL10−/− mice colonized with AIEC alone or treated with the NSAID alone." (PMID 36656595, 2023). "Interleukin (IL)-10 signaling by innate immune cells plays a critical role in the regulation of mucosal homeostasis, independent of effector T cells, in the T cell transfer colitis model." (PMID 38012544, 2023). "While female IL-10 mice may develop worse colitis on occasion, this is not a consistent observation." (PMID 36869359, 2023).
colitis (continued). "Nevertheless, though the CD3+Foxp3+ MLN cells were decreased, the concomitant reduction in IL-10 producing lymphocytes at these draining lymph nodes, together with an outstanding splenic TNF production, reiterates the pro-inflammatory potential of MLT in experimental colitis." (PMID 36838425, 2023). "Thus, mice (IL-10 knockout) developing inflammation of the intestinal mucosa under normal breeding conditions did not develop colitis under germ-free conditions." (PMID 35630457, 2022). "Furthermore, an anti-MAdCAM-1 antibody, which does not bind CD103, also hastened colitis in adult IL-10−/− mice." (PMID 34433904, 2022). "In addition, several studies have reported elevated IL-10 levels in the PBMCs of IBS patients because elevated circulatory IL-10 levels in IBD patients are attributed to inflammatory reaction of colitis." (PMID 35721806, 2022). "Interestingly, similar effects were observed in a model of chemically induced colitis using dextran-sodium sulfate (DSS) and also in IL-10 deficient mice (IL10-/-), both exhibiting increased susceptibility to non-pathogenic E. coli." (PMID 35572549, 2022). "Here, we asked whether CCR2 is necessary for the development of colitis in mice lacking the receptor for IL10." (PMID 35013585, 2022). "Although colitis in this model was accredited to the production of the Th1 cytokine IFN-γ, enhanced emergence of IL-17A+IFN-γ population of T cells and suppression of populations of Foxp3+ and IL-10-producing regulatory T cells was attributed to IL-23R signalling in T cells." (PMID 36012618, 2022). "Nonetheless, the level of colonic IL-10 (an anti-inflammatory cytokine) in ghrelin-treated mice increased up to two times higher than normal mice without colitis, which suggested that IL-10 contributed to the therapeutic benefits of ghrelin on colonic inflammation." (PMID 35050153, 2022). "However, the administration of F nucleatum to colitis‐associated mouse models (eg, BALB/c IL‐10−/− and BALB/c T‐bet−/− × Rag2−/−) neither accelerates gut inflammation nor increases the number of colorectal adenomas." (PMID 35244953, 2022). "In addition, colitis mice that were administered BMVs from normal and DSS-miR-200b-3p feces showed reduced levels of inflammation-related parameters in the serum and colon, including decreased IL-6 and TNF-α levels and increased IL-10 levels." (PMID 36176029, 2022). "Animal studies of colitis had demonstrated that B. fragilis NCTC 9343, B. thetaiotaomicron DSM 2079, and B. cellulosilyticus DSM 14838 improved intestinal histopathological injury and increased anti-inflammatory cytokine IL-10 and Treg cells levels by increasing the number of CD4+ CD45RBlow T cells." (PMID 36531989, 2022). "These colitis mice also showed a shorter colonic length, increased colonic weight and index of colonic weight, DAI, and pathological damage score, as well as increased levels of pro-inflammatory cytokines TNF-α, IL-1β, IL-6, and IL-12p70, and decreased the level of anti-inflammatory cytokine IL-10." (PMID 36310616, 2022). "In our experiment, the results of the multiplex immunoassay showed a partial change in ILC3-associated cytokines such as IL-22 and GM-CSF, but the more noticeable difference was in ILC2-derived cytokines, including IL-10, which could modulate DSS-induced colitis through a macrophage–ROS–NO axis." (PMID 36101343, 2022). "Additionally, IL-10 levels also increased in DSS-induced colitis mice after CsCA administration, but there was no statistical difference (P > 0.05)." (PMID 36084127, 2022). "Moreover, cholecystectomy also reduced mRNA levels of pro-inflammatory cytokines (Il1β, Il6, Tnfα); while it did not affect anti-inflammatory cytokines (Il4, Il10) in colonic tissues under colitis status." (PMID 36050867, 2022).